FBXO22 (F-box protein 22)
Description:
Substrate-recognition component of the SCF (SKP1-CUL1-F-box protein)-type E3 ubiquitin ligase complex that is implicated in the control of various cellular processes such as cell cycle control, transcriptional regulation, DNA damage repair, and apoptosis. Promotes the proteasome-dependent degradation of key sarcomeric proteins, such as alpha-actinin (ACTN2) and filamin-C (FLNC), essential for maintenance of normal contractile function. Acts as a key regulator of histone methylation marks namely H3K9 and H3K36 methylation through the regulation of histone demethylase KDM4A protein levels. Under oxidative stress, promotes the ubiquitination and degradation of BACH1. Mechanistically, reactive oxygen species (ROS) covalently modify cysteine residues on the bZIP domain of BACH1, leading to its release from chromatin and making it accessible to FBXO22. Upon amino acid depletion, mediates 'Lys-27'-linked ubiquitination of MTOR and thereby inhibits substrate recruitment to mTORC1. Also inhibits SARS-CoV-2 replication by inducing NSP5 degradation.
Synonyms: FBX22; FISTC1; TYMAS
Tractability: PROTAC: ubiquitination databases record sites on it; its protein half-life has been measured.
Gene: Protein-coding gene on chromosome 15 (75,903,876 to 75,942,511, forward strand). Ensembl gene ENSG00000167196.
Subcellular location: Cytoplasm; Nucleus; Cytoplasm, myofibril, sarcomere, Z line
Pathways (Reactome):
Immune System: Antigen processing: Ubiquitination & Proteasome degradation
Metabolism of proteins: Neddylation
Gene Ontology:
Molecular function: protein binding; ubiquitin-protein transferase activity
Biological process: positive regulation of proteasomal ubiquitin-dependent protein catabolic process; protein modification process; protein polyubiquitination; regulation of skeletal muscle fiber development; SCF-dependent proteasomal ubiquitin-dependent protein catabolic process; ubiquitin-dependent protein catabolic process
Cellular component: cytoplasm; nucleus; cytosol; SCF ubiquitin ligase complex; Z disc
Genetic constraint (gnomAD): Loss-of-function variants: 10 observed, 24.85 expected, observed/expected ratio (o/e) 0.4, 90% interval 0.25 to 0.68. The upper end of that interval is the gene's LOEUF score, 0.68, which puts it in group 2 of 6, group 1 being the genes least tolerant of losing a copy. Missense variants: 381 observed, 440.39 expected, observed/expected ratio (o/e) 0.87, 90% interval 0.8 to 0.94. Synonymous variants: 164 observed, 166.18 expected, observed/expected ratio (o/e) 0.99, 90% interval 0.87 to 1.12.
Homologues: Orthologues: chimpanzee FBXO22 (99% identical), mouse Fbxo22 (92% identical), rat Fbxo22 (92% identical), pig FBXO22 (90% identical), guinea pig FBXO22 (78% identical), dog UBE2Q2 (77% identical), rabbit FBXO22 (66% identical), tropical clawed frog fbxo22 (52% identical), zebrafish fbxo22 (48% identical).
Diseases named in the same sentence as FBXO22 in open-access papers:
FBXO22 is named in the same sentence as 45 diseases in open-access papers, as found by Europe PMC text mining. Sharing a sentence is not in itself a finding about the gene and the disease. The quoted sentences say what the papers report.
breast carcinoma (19 papers, 2019 to 2025). "However, contrary to these reports, lower level of FBXO22 was linked to poor prognosis in breast cancer patients and renal cell carcinoma patients." (PMID 36127346, 2022). "FBXO22 exhibited a dual function in breast cancer, enhancing cell proliferation while concurrently suppressing metastatic processes." (PMID 38187284, 2024). "Our previous study discovered that FBXO22 prevents breast cancer progression by directly catalyzing HDM2 ubiquitination degradation." (PMID 38519492, 2024). "Surprisingly, FBXO22 exhibited both antimetastatic functions and protumorigenic effects on breast cancer development and progression." (PMID 39153212, 2024). "Specifically, targeting Fbxo22 can be taken as a promising strategy for cancer therapy, since the inhibitory role of Fbxo22 has been proved in different malignancies, including breast cancer." (PMID 36112263, 2023). "Immunoblotting results confirmed that Fbxo22 was highly expressed in luminal-type breast cancer cells MCF-7, T47D, and ZR-75–1 compared to MCF-10A cells." (PMID 36112263, 2023). "After overexpression of Fbxo22, breast cancer metastases were reduced in the lung tissue, yet breast cancer metastases were more obvious after co-treatment of Flag-Fbxo22 and HA-KDM5A." (PMID 36112263, 2023). "Fbxo22 also exerts inhibitory function in breast cancer cell migration and invasion by ubiquitinating SNAIL levels." (PMID 36112263, 2023). "The tumor-suppressing characteristics of Fbxo22 in breast cancer have been demonstrated before with its high expression prevented metastasis from the primary tumor site to lung." (PMID 36112263, 2023). "Lysine demethylase 4B (KDM4B) degradation in breast cancer cells is also mediated by FBXO22, leading to modulation of selective estrogen receptor modulator (SERM) activity and thus tamoxifen resistance in estrogen receptor (ER)-positive breast cancer cells." (PMID 35141150, 2021). "FBXO22 promotes proliferation in breast cancer and lung cancer, but suppresses migration and metastasis." (PMID 32793396, 2020). "The stability of HDM2 oncoprotein is regulated by FBXO22 by ubiquitin-dependent degradation in breast cancer cells." (PMID 32793396, 2020). "FBXO22 proliferative role in primary breast cancer, and degrades SNAIL through ubiquitination to exert an anti-metastatic effect." (PMID 30808376, 2019). "GLS, YY1AP1, FBXO22, KLC1, CUL4A, KITLG, and CYRIB are changed by AS that may be linked to the emergence of breast cancer." (PMID 40384436, 2025). "In addition, FBXO22 acts as a molecular switch to determine the sensitivity of ER+ breast cancers to selective estrogen receptor modulators (SERMs), such as tamoxifen." (PMID 38296976, 2024). "Similarly, a prior study showed that low Fbxo22 expression shared correlation with worse survival in human breast cancer, and knockdown of Fbxo22 promoted breast cancer cell invasiveness." (PMID 36112263, 2023). "Consistently, one previous study also noted the inhibitory role of Fbxo22 in EMT in breast cancer." (PMID 36112263, 2023). "In addition, survival analysis based on ExSurv database revealed that breast cancer patients with high expression of Fbxo22 had a higher survival rate (hazard ratio = 1.557, p-value = 0.024)." (PMID 36112263, 2023). "The oncogenic role of FBXO22 was shown in colorectal, liver, lung and breast cancers, while the suppressive role of cancer metastasis was also been proposed in lung cancer and breast cancer." (PMID 36774506, 2023). "Moreover, upregulation of FBXO22 enhanced proliferation and colony formation in breast cancer cells." (PMID 36127346, 2022). "FBXO22 promoted breast cancer cell growth but inhibited cell metastasis." (PMID 36127346, 2022). "On the other hand, FBXO22 plays a dual role in breast cancer and lung adenocarcinoma." (PMID 36127346, 2022).
breast carcinoma (continued). "However, previous studies have shown that FBXO22 does not only promote cell proliferation but also inhibit migration and metastasis in lung and breast cancer, indicating that FBXO22 has both oncogenic and tumor suppressive roles." (PMID 35141150, 2021). "Consistent with our current findings and further supporting the importance of CRL in the regulation of tumor cell proliferation, the suppression of CRL activity using FBXO22 silencing inhibited cancer progression through targeting of HDM2 for degradation in breast cancer." (PMID 33499884, 2021). "Interestingly, FBXO22 exhibits a paradoxical dual role of pro-tumorigenic and anti-metastatic function in breast cancer progression." (PMID 35046938, 2021). "Similalry, KDM4B degradation is mediated by FBXO22 in breast cancer cells, resulting in regulation of selective estrogen receptor modulators (SERMs) activity, leading to modulation of tamoxifen resistance in ER-positive breast cancer cells." (PMID 32793396, 2020). "This study indicated that FBXO22 may act as an upstream regulator and play a dual role in mammary cancer by inducing Snail degradation: promotion of proliferation and suppression of metastasis." (PMID 32793396, 2020). "However, it was also reported to exert its antimetastatic role in breast cancer and renal cell carcinoma progression, and a low level of FBXO22 in tumor tissues predicts a poor outcome in ER-positive/HER2-negative breast cancers." (PMID 31217475, 2019). "In addition, a recent study has shown that FBXO22 plays a dual role in controlling breast cancer growth and metastasis." (PMID 30808376, 2019). "FBXO22 has been shown to promote breast cancer cell and hepatocellular carcinoma cell growth." (PMID 31217475, 2019). "For instance, our recent report revealed that FBXO22 targets HDM2 and mediates its ubiquitination degradation, which prevents breast cancer cell invasion and metastasis." (PMID 38519492, 2024). "The expression of FBXO22 has been reported to be upregulated in hepatocellular carcinoma, pancreatic carcinoma, and melanoma and downregulated in ER+HER2- breast cancer and renal cell carcinoma." (PMID 38296976, 2024). "Therefore, we speculated that in breast cancer, Fbxo22 may degrade KDM5A protein by ubiquitination." (PMID 36112263, 2023). "Paradoxically, overexpression of FBXO22 blocked EMT formation, cell migration and invasion, and metastasis in breast cancer, lung cancer, and RCC." (PMID 36127346, 2022). "FBXO22 has also been shown to target MDM2 proto-oncogene (HDM2) for ubiquitination and degradation, thereby inhibiting breast cancer invasion and metastasis." (PMID 35141150, 2021). "Moreover, FBXO22 inhibited tumour cell invasion and metastasis by controlling human homologue of mouse double minute 2 (HDM2) degradation in breast cancer." (PMID 39153212, 2024). "However, low expression of Fbxo22 was observed in TNBC cells MDA-MB-231, MDA-MB-468, and Hs578T compared to luminal type breast cancer cells." (PMID 36112263, 2023). "Deletion of Fbxo22 itself does not affect the growth of T47D breast cancer tumors in female NOD/Scid mice and only slightly reduces the proliferation and clone abilities of MDA-MB 231 cells." (PMID 36112263, 2023). "Expression of F-box only protein 22 (FBXO22) in HCC, UBR5 (ubiquitin protein ligase E3 component N-recognin 5) in colon cancer and PSMD2 (26S proteasome non-ATPase regulatory subunit 2) in breast cancer is upregulated; these genes regulate p21 stability by mediating ubiquitylation of p21." (PMID 31416295, 2019).
lung carcinoma (19 papers, 2019 to 2025). "Our results showed that FBXO22-deficient lung cancer cells showed worse radiation-induced DNA damage and greater radiosensitivity than control cells." (PMID 38296976, 2024). "In the present study, we found that FBXO22 was aberrantly highly expressed in lung cancer and that high expression of FBXO22 was associated with poor clinical prognosis." (PMID 38296976, 2024). "Lignito’s results showed that loss of Keap1 or Fbxo22 induces metastasis in a Bach1-dependent manner and causes a notable increase in the metastatic phenotype in mouse models of lung cancers." (PMID 32629428, 2020). "To test whether the anti-invasive effect of paeoniflorin depends on the degradation of BACH1 via FBXO22, we repeated the invasion experiments with paeoniflorin in both FBXO22-proficient and -deficient lung cancer cells." (PMID 40716152, 2025). "Because the loss-of-function mutations of LKB1 and the gain-of-function mutations of K-RAS are two major lung cancer-driven genes, we further evaluated whether FBXO22 expression predicts prognosis related to the status of LKB1and K-RAS in lung adenocarcinoma patients." (PMID 31217475, 2019). "FBXO22 is aberrantly highly expressed in lung cancer and participates in radioresistance formation by activating the FOXM1/Rad51 axis." (PMID 38296976, 2024). "In conclusion, FBXO22 is highly expressed in lung cancer, and its expression is a predictor of poor prognosis." (PMID 38296976, 2024). "To clarify the biological role of FBXO22 in lung cancer radiotherapy, we silenced the expression of FBXO22 with two different methods (SiRNA and CRISPR-Cas9 technology)." (PMID 38296976, 2024). "Here, we found that FBXO22 was aberrantly highly expressed in lung cancer and that FBXO22 knockdown increased the radiosensitivity of lung cancer cells." (PMID 38296976, 2024). "In summary, deguelin was identified as a small molecule inhibitor of FBXO22 that enhances lung cancer radiosensitivity in vitro and in vivo." (PMID 38296976, 2024). "Collectively, our findings indicate that overexpression of FBXO22 in lung cancer is a biomarker of poor prognosis and that FBXO22 silencing increases lung cancer radiosensitivity." (PMID 38296976, 2024). "Given the function of FBXO22 in lung cancer radioresistance, searching for drugs targeting FBXO22 has profound clinical significance." (PMID 38296976, 2024). "Considering the effect of FBXO22 in inducing lung cancer radioresistance, searching for FBXO22 inhibitors has important clinical applications." (PMID 38296976, 2024). "Overall, our results demonstrate that deguelin can inhibit the function of FBXO22 and enhance lung cancer radiosensitivity in a Rad51-dependent manner." (PMID 38296976, 2024). "Accordingly, deguelin is a potential inhibitor of FBXO22 and a safe and effective radiosensitizing agent for lung cancer radiotherapy." (PMID 38296976, 2024). "Consistent with the database results, FOXM1 was downregulated upon FBXO22 silencing and promoted Rad51 expression at the transcriptional and translational levels in lung cancer cells." (PMID 38296976, 2024). "Deguelin was identified as a functional inhibitor of FBXO22 by utilizing the CMap database and was shown to increase lung cancer radiosensitivity in vitro and in vivo with a favorable safety profile, exhibiting substantial clinical translation prospects." (PMID 38296976, 2024). "The findings indicated that FBXO22 was remarkably overexpressed in lung cancer and that high expression of FBXO22 was correlated with short overall survival of patients, suggesting that FBXO22 is a biomarker of poor prognosis in lung cancer." (PMID 38296976, 2024). "In lung cancer cells, FBXO22 overexpression inactivates liver kinase B1 and enhances lung cancer cell growth." (PMID 39153212, 2024).
lung carcinoma (continued). "To elucidate the downstream mechanism of FBXO22-induced lung cancer radioresistance, we performed RNA-seq in scrambled and FBXO22-silenced A549 cells." (PMID 38296976, 2024). "Collectively, our results illustrate that FBXO22 induces lung cancer radioresistance by activating the FOXM1/Rad51 axis and provide preclinical evidence for the clinical translation of this critical target." (PMID 38296976, 2024). "In conclusion, our study reveals a new biological function of FBXO22 in promoting lung cancer radioresistance." (PMID 38296976, 2024). "NRF2 promotes BACH1 accumulation by inhibiting the heme- and FBXO22-mediated degradation of BACH1 in lung cancer." (PMID 35154476, 2022). "This was confirmed in nonsmall cell lung cancer A549 cells, where FBXO22 overexpression enhanced cyclin-dependent kinase 4 (CDK4) protein levels and promoted cell proliferation." (PMID 35141150, 2021). "FBXO22 mediates lys-63-linked liver kinase B1 (LKB1) polyubiquitination and inhibits its kinase activity, thereby inhibiting nonsmall-cell lung cancer (NSCLC) cell growth." (PMID 35141150, 2021). "Taken together, our findings demonstrate that FBXO22 degrades tumor suppressor genes by ubiquitination and inhibits the cell cycle to promote nonsmall cell lung cancer progression." (PMID 35141150, 2021). "Recently, FBXO22 was identified to mediate the Bach1 degradation and inhibit migration in lung cancer cells." (PMID 32793396, 2020). "The accumulation of NRF2 in lung cancer promotes the stabilization of BACH1, and the loss of KEAP1 or FBXO22 induces metastasis in a BACH1-dependent manner." (PMID 32429232, 2020). "In support of the oncogenic role of FBXO22 in lung cancer, the high expression of FBO22 is correlated with poor overall survival in lung cancer patients." (PMID 32793396, 2020). "Then we also examined the relationship between FBXO22 mRNA expression and patients outcome using two different cohorts of lung cancer patients." (PMID 31217475, 2019). "In summary, our study shows that FBXO22 mediates K63-linked polyubiquitination of LKB1, thereby suppresses LKB1 activity and promotes lung cancer cell growth through LKB1/AMPK/mTOR pathway." (PMID 31217475, 2019). "Next, we also found the endogenous interaction between FBXO22 and LKB1 in LKB1-deficient A549 and LKB1-proficient H1299 lung cancer cells." (PMID 31217475, 2019). "To explore the biological function of FBXO22 in lung cancer, we initially sought to examine FBXO22 expression in clinical samples." (PMID 31217475, 2019). "Taken together, all these data propose that FBXO22 accelerates lung cancer cell growth through inhibiting LKB1/AMPK/mTOR signaling." (PMID 31217475, 2019). "The recent lines of evidence revealed that NRF2 inhibits the heme- and Fbxo22-mediated degradation of Bach1 by inducing Ho1, and activates the lung cancer metastasis." (PMID 31884422, 2019). "Mechanically, FBXO22 promotes NSCLC cell growth through inhibiting LKB1/AMPK/mTOR signaling pathway, which reinforces the oncogene function of FBXO22 in lung cancer." (PMID 31217475, 2019). "Our study provides new insights into the upstream regulation of LKB1 activation and identifies FBXO22 as a potential therapeutic target for lung cancer treatment." (PMID 31217475, 2019). "While FBXO22 was shown to promote heme-induced degradation of BACH1 in lung cancer cells, the detailed mechanism of their interaction remains unclear." (PMID 39758820, 2025). "Altogether, our findings demonstrate that our BACH1 signature successfully identified paeoniflorin as a novel BACH1 “inhibitor”, revealing its ability to promote BACH1 degradation via FBXO22 and to suppress lung cancer cell invasion in a FBXO22-BACH1 dependent manner." (PMID 40716152, 2025). "Importantly, the knockdown of FBXO22 significantly reduced the responsiveness of lung cancer cells to deguelin, suggesting that deguelin functions in an FBXO22/Rad51-dependent manner." (PMID 38296976, 2024).